TIGIT (T cell immunoreceptor with Ig and ITIM domains)
Diseases named in the same sentence as TIGIT in open-access papers (continued):
Sharing a sentence is not in itself a finding about the gene and the disease.
cancer (continued). "Efficacy of antibody blockade of TIGIT in cancer immunotherapy is currently widely being investigated in both pre-clinical and clinical studies." (PMID 34367161, 2021). "Regarding the co-expression of multiple co-inhibitory receptors, we observed similar frequencies of double positive (TIGIT+PD-1+ / TIGIT+TIM-3+ or TIGIT+CD39+) cells in both cancer entities." (PMID 34820398, 2021). "T cell immunoglobulin and ITIM domain (TIGIT) is another immune checkpoint molecule that has recently garnered attention as an emerging target in cancer immunotherapy." (PMID 34830795, 2021). "In this study, we showed the pan-cancer landscape of aberrant TIGIT expression across different tumors for the first time." (PMID 34795387, 2021). "Recent immunotherapies have used PD-1, CTLA4, and TIGIT inhibitors to enhance T cell response in cancer patients." (PMID 35069521, 2021). "We identify gaps in our current understanding of TIGIT’s roles in cancer immunity that require further study and, based on current insights, we provide recommendations for its positioning in cancer immune checkpoint therapy." (PMID 34367161, 2021). "PD-L1 and PVR, the respective ligands for PD-1 and TIGIT, are upregulated in cancer and chronic viral infection." (PMID 33767694, 2021). "CD155, expressed in cancer cells, binds to TIGIT on T cells to induce direct inhibitory signals and disrupt CD226-mediated T cell activation." (PMID 34025655, 2021). "Our results revealed the positive correlation between TIGIT and TIICs in 3 cancer types with poor prognosis." (PMID 34795387, 2021). "The results suggested that UBE2C expression was positively associated with the immune checkpoint-related genes in 31 cancers, which mainly included CD274, CTLA4, HAVCR2, LAG3, PDCD1, PDCD1LG2, SIGLEC15, and TIGIT." (PMID 34858987, 2021). "The results revealed that CD161 was positively correlated with marker genes of exhausted T cells, immune activating genes, and immunosuppressive genes in pan-cancer, such as TIGIT, PDCD1, LAG3, CTLA4, STING1, CD96, and IDO1." (PMID 34305920, 2021). "We found that CD161 was positively correlated with marker genes of exhausted T cells, immune activating genes, and immunosuppressive genes in pan-cancer such as TIGIT, PDCD1, LAG3, CTLA4, STING1, CD96, and IDO1." (PMID 34305920, 2021). "In 11 of the 33 cancer types TIGIT was positively correlated with the expression of at least one MMR genes." (PMID 34795387, 2021). "While recent advances in cancer immunotherapy showed synergistic effects of simultaneous blockade of PD-1 and TIGIT, subsequent studies demonstrated the requirement of CD226 expression for this approach." (PMID 34712231, 2021). "To further investigate the underlying mechanism of immune inhibition of TIGIT signaling, we analyzed the relationship of TIGIT expression with multiple immune checkpoint markers across 33 cancer types." (PMID 34795387, 2021). "T cell immunoreceptor with Ig and ITIM domains (TIGIT) is a suppressive receptor in T-cells that was recently shown to contribute to NK cell dysfunction in cancer." (PMID 32153582, 2020). "The Fap2 protein secreted by F. nucleatum interacts with TIGIT and inhibits natural killer (NK) cell–mediated immunosurveillance of cancer." (PMID 32993020, 2020). "PRDM1 expression positively correlates with the expression of LAG3, CTLA4, PDCD1 (PD-1), CD274 (PD-L1), PDCD1LG2 (PD-L2), TIGIT in the majority of 33 cancer types." (PMID 33384601, 2020). "Between 20 and 90% of resting NK cells express TIGIT and levels are increased by acute and chronic viral infections or cancers." (PMID 32432050, 2020). "TIGIT is an important marker expressed by suppressive T-cells as demonstrated in other cancer settings." (PMID 32899203, 2020). "Since co-inhibitory receptors, such as PDCD1 and TIGIT, are targets for cancer immunotherapies, we then focused on analyzing the preferential enrichment of exhausted CD8+ T cells in GC." (PMID 32039830, 2020).
cancer (continued). "Though TIGIT clearly suppresses NK cell activity, the role it plays in maintaining NK cell tolerance in cancer was not fully understood until recently." (PMID 32153582, 2020). "The Skyscraper 02 (clinicaltrials.gov: NCT04256421) is a phase III trial that will investigate the role of tiragolumab, a novel cancer immunotherapy designed to bind to TIGIT, an immune checkpoint protein expressed on immune cells." (PMID 32899891, 2020). "Generally, PRDM1 expression positively correlates with the expression of LAG3, CTLA4, PDCD1 (PD-1), CD274 (PD-L1), PDCD1LG2 (PD-L2), TIGIT in the majority of 33 cancer types." (PMID 33384601, 2020). "We also found that TIGIT blockade augmented pNK cytotoxicity, reinforcing the importance of the DNAM-1/TIGIT axis in NK responses against cancer cells infected with oncolytic adenoviruses." (PMID 32195317, 2020). "Although TIGIT has recently become a new immune checkpoint for cancer immunity, few studies have reported on TIGIT expressed by MSCs." (PMID 32849489, 2020). "Among the ligands that interact with CD155, TIGIT is of particular interest to the development of NK cell therapies owing to its overexpression on NK cells in various cancers." (PMID 32532329, 2020). "In a clinical trial, a pharmaceutical cocktail containing anti-TIGIT (Etigilimab) and an anti-PD-1 (Nivolumab) antibody was used to eradicate cancer and restore immune response, and the results of this trial showed the tolerability of therapy." (PMID 32640575, 2020). "TIGIT has recently emerged as a major target in cancer immunotherapy (Harjunpää and Guillerey, 2020)." (PMID 33490104, 2020). "A small molecule liothyronine was discovered to serve as a potential candidate for cancer immunotherapy by blocking the immune checkpoint TIGIT/PVR." (PMID 32894141, 2020). "As such, we will focus our discussion to recent findings regarding the role of TIGIT in regulating NK cell responses to cancer." (PMID 33613552, 2020). "The high frequency of TIGIT (and PD-1) expressing lymphocytes in cancers highlights considerable opportunities for cotargeting with checkpoint inhibitors." (PMID 30733837, 2019). "In this study, we provided new evidence that TIGIT can be expressed in cancer cells and that aspirin can attenuate the TIGIT expression in CRC cells." (PMID 31090213, 2019). "In this paper, we found that aspirin attenuates cancer cell proliferation and induces CRC cell apoptosis by down‐regulating the expression of TIGIT, which provides new evidence for the application of aspirin in cancer treatment." (PMID 31090213, 2019). "We observed co-expression of PD-1, Tim-3, and TIGIT on cytotoxic (CD8) TILs in multiple types of cancer, which indicates the phenotype of CD8 TILs for future in vitro analysis of dysfunctional T cells." (PMID 31709176, 2019). "At present, humanized anti-TIM3 (TSR-022), anti-LAG3 (MK-4280), and anti-TIGIT (BMS-986207) antibodies against various cancers are under clinical trials." (PMID 31379886, 2019). "In multiple preclinical cancer models including AML, TIGIT expression was strongly associated with expression of other co-inhibitory molecules such as PD-1, Tim-3 and Lag-3, indicating the potential need for targeting multiple checkpoints in AML treatment." (PMID 29855615, 2018). "It was also observed that the binding of Fap2 to human inhibitory receptor TIGIT protects the cancer cells from the immunosurveillance activity of NK cells, which, in effect, would allow the cancer cells to grow and proliferate." (PMID 29619076, 2018). "PVR and PD-L1, as the corresponding ligands of TIGIT and PD-1, respectively, were also expressed in these murine cancer cell lines." (PMID 30555485, 2018). "During the short ATI phase, TIGIT expression, which is up-regulated on exhausted T cells in cancer as well as during chronic viral infection including HIV-infection, did not change significantly." (PMID 29324842, 2018).
cancer (continued). "IL-27 induces inhibitory molecules including PD-1, Tim-3, LAG-3, TIGIT, and IL-10, which overlap with the mediators of T cell exhaustion, in chronic viral infections and cancer." (PMID 28545567, 2017). "Among them, LAG-3, Tim-3, and TIGIT are emerging immune checkpoints under preclinical and clinical development for cancer therapy." (PMID 28545567, 2017). "Similar to PD-1, TIM-3, and LAG-3, TIGIT is upregulated on exhausted T cells in both chronic viral infections and cancer." (PMID 26347741, 2015). "TIGIT has also been shown to play a crucial role in other types of cancer." (PMID 41596586, 2026). "Six of these—CD5, CTLA4, TIGIT, LAIR1, PDCD1, and TNFRSF14—encode proteins that have been identified as immune checkpoints, defined broadly as receptors on immune cells that are exploited by cancer cells to escape the immune response." (PMID 39887658, 2025). "Moreover, anti‐TIGIT clinical trials for cancer patients are ongoing, and our data further support the potential benefit of targeting TIGIT in the very old." (PMID 40100045, 2025). "As we move forward in the field of cancer immunotherapy, the exploration of TIGIT, VISTA, STING, GITR and TIM-3 within GI cancers expands our arsenal of therapeutic strategies and enhances our understanding of the intricate interactions between cancer and the immune system." (PMID 40777027, 2025). "Strikingly, ACACA expression exhibited significant negative correlations with the immune checkpoint-related genes (PDCD1, LAG3, LAGLS9, IDO1, CD244, CTLA4 and TIGIT), while showing positive associations with other genes (TGFBR1, KDR, IL10RB, CD160 and CD274) across most cancer types." (PMID 41169354, 2025). "Notably, genes such as HAVCR2, PDCD1LG2, CD274, and TIGIT exhibited the strongest positive correlations with STX7 across more than 20 cancer types, suggesting a role for STX7 in immune checkpoint-mediated regulation." (PMID 40999361, 2025). "However, each gene in different cancers positively correlated (p < 0.05) with either its mRNA expression or CNVs, e.g., TIGIT in ACC, LAG3 in UVM, HAVCR2 in LUSC, LAYN in OV and PDCD1 in BLCA." (PMID 40076932, 2025). "Using anti-TIGIT mAb alone and with other anti-cancer agents." (PMID 40567374, 2025). "This suggests that the upregulation of these genes, including PDCD1, TIGIT, and LGALS9, may be associated with a more favorable immune response and a lower risk of cancer progression or recurrence." (PMID 40747615, 2025). "Similarly, TIGIT blockade has been shown to enhance T cell function in both cancer and infectious diseases." (PMID 40231264, 2025). "This speculation is different from what has been found in the context of cancer, where TIGIT is considered a marker for T cell exhaustion and the TIGIT-expressing cell are mostly dysfunctional." (PMID 40526725, 2025). "LAG-3 is a key immune co-inhibitory receptor alongside PD-1 and TIGIT, reported in various cancers." (PMID 41300994, 2025). "Similarly, a promising area of investigation in SETD2-mutated cancer is into immune checkpoint expression, such as HAVCR2, CTLA-4, or TIGIT or biomarkers such as CDCP1 and AXL." (PMID 41228333, 2025). "TIGIT is a co-inhibitory receptor of CD155 in malignant tumors." (PMID 41181119, 2025). "Therefore, dual treatment with TIGIT inhibitors holds great promise for overcoming immunotherapy resistance and improving cancer response rates." (PMID 41233805, 2025). "In addition, TIGIT enhances the function of Tregs, indicating its immunosuppressive role in cancer biology." (PMID 39531203, 2025). "Moreover, the levels of other checkpoint molecules, such as TIM3, TIGIT, and CTLA4, were significantly associated with CXCL5 in multiple forms of cancer." (PMID 39670859, 2025). "For instance, the high T cell exhaustion levels could be reversed with TIGIT/PD-1 co-blockade using the currently approved immune checkpoint inhibitors in cancer research." (PMID 38702419, 2024). "TIGIT plays a crucial role in cancer immunology by mediating immune suppression." (PMID 39465721, 2024).
cancer (continued). "Additionally, we focus on next-generation ICIs, Tim-3 and TIGIT inhibitors, exploring their influence on T-cell function, role in cancer treatment, and potential for cardiac irAEs." (PMID 38375475, 2024). "Moreover, TIGIT is significantly overexpressed by Tregs in the peripheral blood mononuclear cells of both healthy individuals and cancer patients, with further upregulation within TME." (PMID 38375475, 2024). "Notably, the IHC results obtained from both cancer and adjacent tissues also confirmed the significantly elevated expression of TIGIT in TNBC." (PMID 38216949, 2024). "TIGIT is one of the most potent anti-cancer targets using ICIs." (PMID 39064019, 2024). "Blocking TIGIT may enhance T‐cell activation and restore exhaustion in preclinical murine models and cancer patients." (PMID 38279870, 2024). "TIGIT has been identified as an immune checkpoint in several autoimmune diseases and cancers." (PMID 38418707, 2024). "Anti‐TIGIT targeting Tregs possesses strong potential for cancer immunotherapy, and targeting Tregs may also contribute to cancer immunotherapy efficacy when used as monotherapy or in combination with ICB antibodies." (PMID 38783893, 2024). "Finally, we gathered the IC50 of a wide variety of drugs among different cancer cell lines through the GDSC and CTRP databases and tried to explore the possible associations with the corresponding CXCL13, HAVCR2, LAG3, TIGIT, PDCD1, and LAYN mRNA values." (PMID 39064019, 2024). "The positive association between CD27 and TIGIT, CD48 in the majority of cancers suggested a complete co-expressing landscape, and our data demonstrated that CD27 expression was strongly connected with various immunological checkpoints in varied immunocytes and unique T cells." (PMID 38169519, 2024). "To this end, we explored the mutation rate of the Tex signature genes in pan-cancer, and we observed a 2–3% SNV mutation frequency of PDCD1, LAG3, TIGIT, HAVCR2, and LAYN mainly in UCEC and SKCM, with HAVCR2 and TIGIT having the highest mutation frequencies (24% and 23% of samples, respectively)." (PMID 39064019, 2024). "TIGIT has emerged as an attractive immune checkpoint for the cancer therapy." (PMID 38279870, 2024). "In this manner, TIGIT impairs antitumoral immunity and sustains cancer development." (PMID 38612483, 2024). "Although these findings could provide valuable clues about the relationship between TIGIT and NF-κB, further studies focusing on cancer are essential to find new approaches to cancer treatment." (PMID 38418707, 2024). "Indeed, several studies have confirmed that the TIGIT-NECTIN2 signal functioned to create immunosuppressive environment in other cancers." (PMID 39474422, 2024). "Some common and classical immune checkpoint genes such as LAG3, CD27, and TIGIT were most and significantly expressed in pattern B. The antitumor immune cycle works by activating and enhancing the immune system's ability to recognize and destroy cancer cells." (PMID 38322112, 2024). "In addition, our results highlight the prominent role of other surface receptors of CTLs and NK cells, such as TIGIT and CTLA-4, as actionable co-inhibitory signals beyond PD-1 in advanced/high-risk cSCCs enriched in hybrid E/M and mesenchymal cancer cells." (PMID 38914547, 2024). "Moreover, cancer cells tend to inhibit activating receptor expression on NK cells and upregulate inhibitory receptor expression, such as TIGIT, on NK cells." (PMID 38893071, 2024). "We corroborated in cSCC patient samples that the frequency of GzmB+ cells decreased and the frequencies of CD8+PD-1+, CD8+LAG-3+, CD8+TIM-3+ and CD8+TIGIT+ cells increased in mixed and mesenchymal patient cSCCs, which are those tumors enriched in hybrid E/M and mesenchymal cancer cells." (PMID 38914547, 2024).
cancer (continued). "The scope of this review is to summarize approaches that direct target CD155 either as receptor for Poliovirus to address oncolytic virus action on cancerous cells or as a ligand for DNAM-1 and TIGIT immune receptors to favor a more efficient anti-cancer immune response." (PMID 37629138, 2023). "TIGIT expression on Tregs also suppresses T-cell activation in cancer." (PMID 37835436, 2023). "Indeed, the efficacy of the anti-TIGIT + anti-PD-1/PD-L1 combination has already been shown in different cancers, excepting NB." (PMID 37444427, 2023). "TIGIT on T cells can suppress the costimulatory abilities of dendritic cells (DCs) and increase anti-inflammatory cytokines such as IL-10, thus inhibiting T cell responses indirectly by reducing cancer antigen presentation." (PMID 35794399, 2023). "Moreover, the blockade of TIGIT on immune cells or CD155 on cancer cells was shown to promote the cytotoxic effects of immune cells." (PMID 37345111, 2023). "Encouraging results presented in 2021 suggested that the combination of anti-TIGIT and anti-PD-L1 cancer immunotherapies could represent a novel approach in cancer." (PMID 37427115, 2023). "Researchers have found a number of immune checkpoint signals in cancers that could confer strong immunosuppression on cancer cells by combining ligands with inhibitory immunoreceptors, such as PD-1, TIGIT, CTLA-4, BTLA, LAG3, and TIM3." (PMID 36895440, 2023). "Indeed, different anti-TIGIT Ab have been used in preclinical studies and, recently, in cancer patients." (PMID 37444427, 2023). "TIGIT has diverse immunosuppressive effects on the cancer immunity cycle, including the inhibition of natural killer cell effector function, suppression of dendritic cell maturation, promotion of macrophage polarization to the M2 phenotype, and differentiation of T cells to regulatory T cells." (PMID 37291608, 2023). "TIGIT is a promising novel immunotherapy target for cancers." (PMID 36880420, 2023). "Cancer cells utilize the TIGIT pathway to evade immunosurveillance, and anti-TIGIT antibodies may amplify immune responses by inhibiting its binding to CD155 and CD112." (PMID 37009054, 2023). "Recent studies suggest that TIGIT blockades and radiotherapy (RT) may have a synergistic relationship, although TIGIT and RT are mechanically two different approaches to cancer treatment." (PMID 37291608, 2023). "Therefore, this study provides insights into the mechanism by which RT and anti-TIGIT therapy interact to improve outcomes in cancer patients." (PMID 35794399, 2023). "Adoptive NK cell therapy in combination with anti-TIGIT treatment could provide an enhanced treatment option for cancer patients." (PMID 37345049, 2023). "However, in cancer, increased TIGIT expression inhibiting NK-cell-mediated cytotoxicity can impair the efficacy of therapeutic agents." (PMID 37444427, 2023). "The blocking of TIGIT/CD155 interaction is a promising approach in cancer immunotherapy." (PMID 37359558, 2023). "Therefore, targeting TIGIT holds clear clinical potential as a cancer treatment, and various TIGIT-targeting mAbs have been evaluated in clinical trials for the treatment of solid tumors since 2016." (PMID 37670328, 2023). "Blocking TIGIT/CD155 interactions is a promising approach in cancer immunotherapy." (PMID 37359558, 2023). "TIGIT was differentially expressed in Pan cancer tissues compared with normal tissues." (PMID 35770416, 2023). "T cell immunoreceptor with immunoglobulin and ITIM domain (TIGIT) is a major inhibitory receptor of both T cells and natural killer (NK) cells and is an emerging target for immune checkpoint blockade for the treatment of cancer." (PMID 37345049, 2023). "For example, the dysregulation of the IR TIGIT and CD226 (a stimulatory receptor that shares CD112 and CD155 ligands with TIGIT) expression in T cells was recently suspected to be involved in severe forms of autoimmune diseases, as well as in cancer and chronic viral infections." (PMID 35821240, 2022).